PPARG (peroxisome proliferator activated receptor gamma)
Diseases named in the same sentence as PPARG in open-access papers (continued):
Sharing a sentence is not in itself a finding about the gene and the disease.
tumor (continued). "Se activates the PPARγ pathway in vitro and in vivo assays, which reduces STAT-5 (signal transducer and activator of transcription 5) levels and blocks the expression of the CITED2 (cAMP-responsive element-binding protein (CBP)) gene, one of the responsible genes for tumor quiescence." (PMID 34199169, 2021). "PPARG expression was not different in the tumor tissue compared to the control tissue." (PMID 32813759, 2020). "Conversely, administration of PPARγ agonist rosiglitazone, an approved drug for the treatment of type II diabetes, augmented CD8+ T cytotoxicity in a myeloid cell-dependent manner and increased tumor destruction in combination with CTLA4 antibody blockade and GVAX." (PMID 32823961, 2020). "However, as reviewed by Carter and colleagues, it is likely that PPARγ activation may affect PAI-1 expression and might reduce uPA expression leading to a less aggressive cell tumor phenotype in breast tissue through NF-kB downregulation." (PMID 33352766, 2020). "Moreover, according to the C1-C6 immune subtypes previously identified by investigators, we classified tumor samples by representative immune signatures and examined the RNA-seq level of PPARA, PPARD, PPARG, PPARGC1A, and PPARGC1B from C1 to C6, which were all seen to have differential expressions." (PMID 33029111, 2020). "Thus targeting instead the FABP5- PPARγ-VEGF axis, which we suggest, gradually replaces the AR-mediated signalling pathway in tumour progression, could be an alternative way for treatment of CRPC." (PMID 31258834, 2019). "Importantly, a single-ApoSQ injection leads to the enhanced induction of PPARγ and PTEN mRNA and protein expression and to a reciprocal reduction in phosphorylated Akt, as well as in the mRNA levels of Snai1 and Zeb1, within primary tumor tissue." (PMID 30842627, 2019). "However, PPARγ was not involved in the enhancement of 15d-PGJ2 on the anti-tumor activities of topoisomerase inhibitors." (PMID 30815591, 2019). "In addition, several lines of evidence have suggested that the anti-tumor effects of TZDs are independent of PPARγ activation." (PMID 30018246, 2018). "Considering the caspase-1/PPARγ/MCDA axis as an important mechanism to improve TAMs differentiation and tumor aggressiveness, when this axis was damaged with a caspase-1 inhibitor, TAMs cells suffered a specific commitment that negatively affected tumor progression." (PMID 29966227, 2018). "Finally, we also sought to determine whether epidermal PPARγ acts to mediate cutaneous immune responses by examining both CHS and anti-tumor immune responses." (PMID 29228682, 2017). "Of note, the robust expression of PPARG in both adipogenic and non‐adipogenic tumor compartments strongly suggests that its role in AML is not limited to adipogenesis, but may be an oncogenic driver for other cell types." (PMID 28275008, 2017). "However, despite some positive results in several tumor types, PPARG agonists are not widely used due to lack of efficacy." (PMID 28275008, 2017). "Thus, we propose that PPARG activation in AML does not reflect the characteristic adipogenic differentiation of this tumor." (PMID 28275008, 2017). "We confirmed that PPARγ did not mediate the anti-tumor activity of 15d-PGJ2 in RCCs." (PMID 28955990, 2017). "In light of the significant in vitro anti‐proliferative effects of PPARG inhibition on AML cells, we sought to determine whether inhibition of the PPARG pathway could also limit the ability of AML cells to generate tumors in vivo (i.e., tumor initiation capacity)." (PMID 28275008, 2017). "The stimuli related to PPARγ activity gave by Rosiglitazone and GW-9662, did not change the profile of tumor stem cells, translated by the absence of significant change in the percentage of this cell population, measured by the balance between CD24−/CD44+ expression." (PMID 28932171, 2017). "PPARγ was involved in neither the anti-tumor activity nor the synergistic effect of 15d-PGJ2." (PMID 28955990, 2017).
tumor (continued). "PPARγ do not mediate the anti-tumor activity of 15d-PGJ2 in Caki-2 cells." (PMID 28955990, 2017). "Our findings may explain why rosiglitazone exerts anti-tumor effects in certain cancers but not others – cancers with abundant PPARγ-positive macrophages may be sensitive whereas cancers with limited macrophages or PPARγ-negative macrophages may be resistant." (PMID 27692066, 2016). "However, a comprehensive temporal molecular characterization of the LXR and PPARG gene regulatory responses in tumor cells is still lacking." (PMID 27401066, 2016). "Similarly, the volume and weight of the tumours with non-phosphorylated PPARγ (PPARγSA) were smaller compared to the PPARγWT tumours but were larger compared to the LacZ tumours." (PMID 27769068, 2016). "Nonetheless, our genetic rescue and pharmacological experiments indicate that Gpr132 is a very important part of the puzzle and an essential mediator of macrophage PPARγ regulation, because in the absence of Gpr132, the tumor-modulating function of macrophage PPARγ or rosiglitazone is abolished." (PMID 27692066, 2016). "In the present study, activation of the PPARγ pathway in lal−/− MDSCs with its ligand 9-HODE not only impaired their stimulatory effects on in vivo tumor growth and metastasis, but also significantly retarded the ability of these MSDCs to block in vitro tumor cell proliferation and migration." (PMID 26625314, 2016). "This lack of relation could be due to methodical problems of PPARγ detection in archived tumor samples and in the complexity of TZD action." (PMID 25866814, 2015). "Among cotreated groups, thymic tumour incidences were not different between genotypes but did significantly decrease by ~3-fold among PPARγ-WT mice compared to their respective DMBA Only-treated PPARγ-WT controls (p < 0.05)." (PMID 25889730, 2015). "Nuclear receptors have also been noted as having tumor suppressive functions including VDR’s protective function in colon cancer; PPARg’s activation in reducing tumorigenicity in many cancer tissue types; TR4 and RARb as tumor suppressors in prostate, and NUR77 and NOR1 as tumor suppressors in AML." (PMID 26217306, 2015). "There were no apparent differences in the PPARγ expression levels in archived tumor specimens between patients with SD and those with PD (Mean [range] H scores in nucleus, 106.4 versus 155.8; H score = ∑[the staining intensity × the occupied percentage of positive cells])." (PMID 24337768, 2014). "Notably, the AKT inhibitor triciribine alone had a cytostatic effect on tumor cells but did not preferentially inhibit CD133+ tumor-initiating cells, whereas the PPARγ agonist rosiglitazone selectively targeted HCC TICs." (PMID 24023668, 2013). "PPARγ and PPARδ modulate cell fate in the mammary gland, suggesting that PPAR agonists or antagonists may have the potential to regulate differentiation and hence tumor progression." (PMID 22538444, 2012). "However, the role of PPARγ in the tumor microenvironment on cancer progression has not been well studied." (PMID 22934105, 2012). "Using a diethylnitrosamine- (DEN-) induced hepatocarcinoma cell (HCC) model, the authors showed that activation of PPARγ by rosiglitazone blocked tumor development in PPARγ wild-type (PPARγ+/+) littermates, whereas it did not alter tumor formation in PPARγ+/− mice." (PMID 23213321, 2012). "These combined data would go against the supposed role of PPARγ as a tumor suppressor and suggest that high levels of PPARγ, in the apparent absence of any ligand, may be promoting cancer cell growth." (PMID 22194735, 2011). "Based on these finding, it appears as if PPARγ may be exerting some other actions rather than regulating tumor growth." (PMID 20885923, 2010). "Interestingly, vaticanol C as well as resveratrol suppressed the expression of COX-2 in several kinds of tumor cell lines (data not shown) whereas vaticanol C is not an activator for PPARγ." (PMID 20504373, 2010).
tumor (continued). "Suppression of tumor growth is most likely achieved by the induction of MKP-1 which leads to the down-regulation of p38MAPK and ERK1/2, a PPARγ-independent event; retardation of metastases is via a PPARγ-dependent pathway which directly decreases CXCR4 and MMP expressions." (PMID 20226009, 2010). "It was also reported thatwhole animal hemizygous knockout of PPARγ had no affect on tumor number or size in APC+/Min mice, an observation that is atvariance with the notion that PPARγ promotes tumor formation in mice that containactivating germ line mutations in the Wnt/APC/β-catenin pathway." (PMID 18615192, 2008). "Notably, at the time of composition ofthis manuscript, we have not yet found any reports stating that PPARγ expressionis downregulated or absent in human tumor versus normal tissues." (PMID 18784849, 2008). "Perinuclear staining of PPARγ was detected in almost all tumor cells from RGZ-treated mice, while no expression could be found in tumors from untreated mice." (PMID 18261208, 2008). "Therefore, although increased PPARγ activation does not initiate tumorformation in normal mammary tissue, once a tumor-initiating event occurs, PPARγ signaling serves as a tumor promoter inthe mammary gland." (PMID 18584037, 2008). "Notably, activation of PPARγ in pre-established tumors had no significanteffect on BrdU incorporation, consistent with the lack of any significanteffect on tumor size." (PMID 18615192, 2008). "This concept may not be suitable for tumor types with elevated“malignant” PPARγ expression/activities." (PMID 18596912, 2008). "Activation of PPARγ through agonists increases functional PTEN protein levels that subsequently induces apoptosis and inhibits cellular growth, which suggests that PPARγ may be a tumor suppressor." (PMID 19096712, 2008). "In this direction, we can suppose that the increase in polyamine catabolic activity, as a result of PPARγ induction without a concomitant downregulation of the polyamine biosynthetic pathway, could be insufficient for counteracting tumour development." (PMID 16854216, 2006). "We could not correlate PPARγ staining with any of the prognostic variables analysed in the group of PTCs, except for tumours presenting a predominantly follicular pattern that were more often negative (80%) than classic PTCs (28%; P=0.01)." (PMID 15238980, 2004). "Thus it has been suggested that high expression of PPARγ and low expression of COX-2 in the tumours might be involved in attenuating the capacity of the tumours to develop more malignant nature." (PMID 15266333, 2004). "Positive PPARγ staining was not correlated with age, gender, tumour size or vascular invasion." (PMID 15238980, 2004). "There is a lack of consensus on whether PPARG acts as a tumor suppressor or a promoter in cancer." (PMID 40303293, 2025). "Furthermore RNA-scope in situ hybridisation for human peptidyl Isomerase B (HuPPIB), demonstrated detectable levels in the NTS and all K0 tumours, suggesting that in the tumours arose from a small sub-population of human cells that were not knocked down for PPARG." (PMID 33654198, 2021). "Our upstream analyses had indicated that TNBC tumor specimens expressed higher levels of HDACs which, in turn, curtails PPARγ-mediated anticancer signaling pathways, suggesting that HDAC inhibition may be required to reverse the brakes on PPARγ-mediated anticancer effects." (PMID 34580286, 2021). "There appears to be a requirement for PPARG in tumour growth and development in vivo, as no PPARG negative tumours developed, it suggests that not only is PPARG able to accelerate tumour growth and development, but it may be essential for the tumour establishment." (PMID 33654198, 2021).
tumor (continued). "Our results suggested that the activation of PPARG expression may inhibit the development and progression of LSCC through the regulation of LSCC upstream regulators and downstream marker genes, which were involved in tumor cell proliferation and protein polyubiquitination/ubiquitination." (PMID 32565768, 2020). "Hence, the mechanisms underlying tumor formation are not established, and although the tumor types mentioned have been shown to express PPARγ it still discussed whether these effects are receptor dependent or -independent." (PMID 22745632, 2012). "The significance of thisdiscrepancy requires additional investigation, but the data are consistent withthe hypothesis that the suppressive effects of PPARγ on established tumors may be due to inhibitionof tumor progression, rather than inhibition of tumor growth." (PMID 18615192, 2008). "Furthermore, the ablation of PPARγ expression in the mouse mammary gland using a Cre- Lox recombination system has demonstrated that no tumors developed in mammary glands lacking PPARγ suggesting that PPARγ is not a tumor suppressor." (PMID 19061500, 2008). "Thus in thismodel, PPARγ does not act as a tumor suppressorgene." (PMID 18584037, 2008). "This aspect of PPARγ articulates with the resurgence ofinterest in metabolism and cancer which has underscored the 50-year oldfindings of Warburg that the metabolism of tumor cells is deranged; aerobicglycolysis rather than oxidative phosphorylation is the mode of tumormetabolism." (PMID 18670615, 2008). "Furthermore, it has been shown that peroxisome proliferator-activated receptor γ (PPARγ) inhibits the expression of GPR132 proteins in macrophages, so targeting the lactate-PPARγ/GPR132 receptor-related pathway may have an inhibitory effect on the pro-tumor effects of TAMs." (PMID 39169402, 2024). "A total of 57.7% of tumor patients were positive for COX-2 and/or PPARγ with a cytoplasmic IRS value >3; 42.3% did not have a value > 3 for either factor." (PMID 33802010, 2021). "However, the glucose uptake was not affected by neither PPARγ agonist nor inhibitor, which might due to the concept that PPARγ could influence other steps of glycolysis, not only depend on uptake of glucose to regulate tumor metabolism." (PMID 32612951, 2020). "Despite the fact that PPARγ and PGC-1α can each act as both tumor promoter and tumor suppressor, there is no clearly defined mechanism that can explain the contradictory dual effects." (PMID 29599799, 2018). "Targeting tumor stroma by drugs not primarily referred to as anticancer drugs and including COX-2 inhibitors, mTOR antagonists and PPARγ agonists has been previously proposed." (PMID 22654896, 2012). "Specifically, the highest PPARG expression level was identified in an HSCC patient in the stage of T1N0M0, which represented a stage that the tumor development was at its earliest stage, with no significant influence on the regional lymph nodes and no metastasis." (PMID 34054937, 2021). "The tumor suppressive effects of PGI2 might in fact be independent of PPARβ/δ and related to activation of PPARγ as seen with synthetic analogues." (PMID 23049921, 2012). "Therefore, like cell culture models lacking a functional TSC1-TSC2 complex, tumor cells from TSC patients display elevated mTORC1 signaling and PPARγ expression." (PMID 19593385, 2009). "Strikingly, TZD treatment resulted more effective in PPARγhep−/− mice than in WT mice, highlighting that (i) TZD antitumor activity is independent of PPARγ; (ii) PPARγ expression reduced TZD activity; therefore in this model PPARγ may support, rather than inhibiting, tumor growth." (PMID 28115925, 2016).
cancer (977 papers, 2001 to 2026). A tumor composed of atypical neoplastic, often pleomorphic cells that invade other tissues. "Aldehyde dehydrogenase 3 family member A1 (ALDH3A1), an enzyme involved in drug metabolism, is negatively correlated with peroxisome proliferator-activated receptor γ (PPARγ) and is implicated in cancer cell resistance to anticancer drugs." (PMID 41278297, 2025). "Activation of PPARγ is linked to antiproliferative, pro-apoptotic, pro-differentiation, anti-inflammatory, and anti-metastatic effects in a variety of cancer cell lines and rodent carcinogenesis models." (PMID 41403929, 2025). "Different PPARs have significant effects on cancer: PPARα is implicated in promoting proliferation, whereas PPARγ exhibits the opposite effect." (PMID 38835342, 2024). "The role of lncRNA MALAT1 in cancer-associated cachexia through inhibition of adipogenesis via regulation of PPARγ has also been reported." (PMID 39199690, 2024). "It was also reported that HNF1α suppresses the occurrence and progression of HCC by inhibiting cancer-associated PPARγ, Wnt, and NF-kB signaling." (PMID 38879600, 2024). "Despite the high PPARG expression in human cancers, the total mutation rate at the oncogene level was relatively low (0.5%)." (PMID 38044948, 2023). "Taken all together, it is deduced that, mechanistically, the upregulation of PPARγ by CLAGS4 of P. pentosaceus GS4 can alter cancer cell metabolism in association with triggering apoptosis in CC." (PMID 36875279, 2023). "Loss of redox status of cancer cells can be prevented by PPARγ antagonist, suggesting PPARγ vital role in this process." (PMID 36875279, 2023). "Given the highest coefficient of PPARG as a risk core gene in our findings, further exploration into the interplay between lipid metabolism and the senescence process in cancer is warranted." (PMID 38154113, 2023). "While various PPARγ agonists have been developed, their application has been limited by hepatotoxicity, cancer risk and cardiac side effects." (PMID 36998980, 2023). "The DSS analysis results showed that high PPARG expression was associated with poor prognosis in six types of cancer, including GBMLGG, LGG, CESC, GBM, THCA, and PAAD." (PMID 38044948, 2023). "PPARγ, once activated, will express its target genes, resulting in the increased expansion and aggressiveness of cancer cells due to overgrowth caused by low apoptosis and high angiogenesis." (PMID 38136624, 2023). "Taken all together, it is inferred that mechanistically, the upregulation of PPARγ by CLA producing probiotic P. pentosaceus GS4 can alter cancer cell metabolism in association with triggering apoptosis in CC." (PMID 36875279, 2023). "By exploring the molecular mechanisms underlying the involvement of PPARG in tumorigenesis, we can uncover new avenues for the treatment of cancer and potentially identify biomarkers for patient stratification and personalized therapeutic approaches." (PMID 38044948, 2023). "Our findings highlight the importance of PPARG in the broader biology of cancer and suggest its potential as a diagnostic and therapeutic target for specific types of cancer." (PMID 38044948, 2023). "Subsequently, we examined the association between PPARG expression heterogeneity and survival outcomes, finding that high PPARG expression in various types of cancer was strongly associated with a poor prognosis." (PMID 38044948, 2023). "The inducible nitric oxide synthase (iNOS) and PPARγ have been linked to cancer development, and studies have shown higher and lower expression of the iNOS and PPARγ, respectively, in tumorous tissues than in non-tumorous tissues." (PMID 35631448, 2022). "Although all PPAR forms are associated with cancer, PPARγ has anticarcinogenic properties, as it promotes apoptosis and restricts cell growth." (PMID 35163356, 2022).